SMYD2 (SET and MYND domain containing 2)
Diseases named in the same sentence as SMYD2 in open-access papers (continued):
Sharing a sentence is not in itself a finding about the gene and the disease.
tumor (56 papers, 2006 to 2026). "Aberrant dysregulation of SMYD2 is associated with tumor aggressiveness and resistance to conventional therapies, justifying its therapeutic potential for NEPC." (PMID 41470892, 2025). "The association between SMYD2 and the tumor immune microenvironment in GC was evaluated using CIBERSORT, ESTIMATE, and TIDE algorithms." (PMID 40777131, 2025). "To explore the association between SMYD2 expression and tumor immune infiltration in GC patients, we performed CIBERSORT analysis in TCGA and GEO datasets." (PMID 40777131, 2025). "The overexpression of the SMYD2 gene in tumor tissues was induced by a genetic mutation, CNAs, and epigenetic control." (PMID 37971632, 2023). "So far, our data revealed a significant impact of SMYD2 in regulating CRC cell death to such an extent that the genetic loss of SMYD2 blocked tumor growth." (PMID 35022391, 2022). "When implanted into the submucosa, the Smyd2 deficient MC-38 cells resulted in tumors that had a significantly reduced tumor size and lower tumor scores, which was similar to the results obtained from the subcutaneous injection experiment." (PMID 35022391, 2022). "Similar to results obtained from the experiments performed with murine tumor cells, SMYD2 deficient HT-29 tumors showed a significant decrease in tumor size and tumor weight." (PMID 35022391, 2022). "To our surprise, we found a significant elevation of cleaved-caspase 3 positive cells in the tumor implants of MC-38 and HT-29 SMYD2 deficient cells compared with MC-38 and HT-29 WT cell implants." (PMID 35022391, 2022). "Comparable numbers of Ki67-positive cells were detected in WT and Smyd2 deficient MC-38 tumor implants and also from the WT and SMYD2 deficient HT-29 tumor implants, suggesting that SMYD2 is dispensable for regulating cell proliferation in vivo." (PMID 35022391, 2022). "With this aim, SMYD2-proficient and -deficient HT-29 cells were implanted into Rag1−/− mice via subcutaneous injection, and tumor development was monitored over time." (PMID 35022391, 2022). "Dysregulated SMYD2 is linked with higher tumor recurrence rate." (PMID 35884603, 2022). "In a large series comprised of 163 primary HCC cases, 74.8% stained positive for SMYD2 using immunohistochemistry, and tumors displaying SMYD2 immunopositivity were significantly associated with vascular invasion, larger tumor size, higher TNM stage and moderate to poorly differentiated phenotypes." (PMID 33050946, 2020). "Notably, high SMYD2 expression was associated with an increased rate of tumor recurrence and disease-related death (P = 0.032 and 0.002, respectively)." (PMID 31754403, 2019). "Furthermore, SMYD2 expression was positively related to tumor mutation burden in GC." (PMID 40777131, 2025). "SMYD2 could regulate multiple tumor-associated signaling pathways." (PMID 40777131, 2025). "In vitro, SMYD2 inhibition decreased tumor-cell Wnt ligand transcription and shifted macrophage responses toward reduced TGF-β expression, in a pattern consistent with reduced Wnt/β-catenin-associated signaling." (PMID 42306568, 2026). "In vivo, SMYD2 pharmacological inhibition with AZ-505 reduced tumor burden and induced pro-inflammatory transcriptional changes." (PMID 42306568, 2026). "SMYD2 expression showed a positive correlation with tumor purity but inverse relationships with immune, stromal, and ESTIMATE scores." (PMID 40777131, 2025). "SMYD2 plays a crucial role in tumor progression and therapeutic resistance through its involvement in AR signaling, tumor aggressiveness, and metastasis." (PMID 41470892, 2025). "Subsequent analysis revealed SMYD2 positively correlated with tumor purity while inversely correlating with immune score, stromal score, and ESTIMATE score." (PMID 40777131, 2025).
tumor (continued). "To identify potential functional circRNAs, we conducted an initial screening of a set of circRNAs that displayed dysregulation in four paired tumor/normal adjacent epithelial tissue samples, along with SMYD2-knockout (SMYD2-KO) cell lines." (PMID 39440063, 2024). "They found that SMYD2 was one of 13 aberrantly expressed genes in LGGs, and that SMYD2 was essential for cell proliferation and tumor formation." (PMID 39765675, 2024). "As expected, gross examination of the lungs revealed a significant metastatic tumor burden in PyMT control mice, while PyMT;Smyd2 mice had fewer visible metastatic nodules in the lungs." (PMID 38296970, 2024). "Activation of the SMYD2/miRNA pathway apparently inhibits sunitinib, weakening its effects and accelerating tumor growth." (PMID 37228649, 2023). "SMYD2 was found to regulate the expression of miR-125b, which in turn regulates the Wnt/B-catenin pathway, acting as a tumor suppressor." (PMID 37228649, 2023). "SMYD2 is widely distributed across normal and tumor tissues and, like SMYD1, is involved in cardiac and skeletal muscle cell differentiation and maturation." (PMID 36816359, 2023). "We used drug-loaded nanoparticles in mice to suppress the expression of SMYD2 and reduce tumor growth as it has already been reported that SMYD2 promotes lung tumorigenesis." (PMID 37513898, 2023). "On a molecular level, SMYD2 promotes cell motility, expands the tumor sphere, and inhibits apoptosis, which is reliant on p53K370 methylation." (PMID 37513898, 2023). "SMYD2, a methyltransferase enzyme, modifies gene transcription and signaling pathways and thus is involved in tumor progression." (PMID 37513898, 2023). "Analysis of primary GC tissue specimens revealed that SMYD2 overexpression was positively correlated with tumor size, invasion, lymph node metastasis, and recurrence rate." (PMID 36816359, 2023). "It has been shown that the level of SMYD2 in TNBC is correlated with tumor progression and poor prognostic outcome; and that inhibition of SMYD2 reverses malignant transformation." (PMID 36520265, 2022). "Overexpression of SMYD2 protein is observed in most primary tumor samples of ESCC, and in some ESCC cell lines." (PMID 36520265, 2022). "In HCC and thyroid cancer, overexpression of SMYD2 is positively correlated with enlarged tumor size, more rapid lymphatic invasion, more potential tumor invasion, and higher TNM stage, as well as worsened overall rate of survival." (PMID 36520265, 2022). "This was associated with decreased expression of the SMYD2 protein substrates EZH2, p65, p-mTOR, and p-MAPK in OC-PF-treated primary tumor samples compared to in the placebo control-treated animal tumors." (PMID 35884603, 2022). "Compared with the control group, the weight of transplanted tumor in the SMYD2 knockdown group was smaller than that in the control group." (PMID 35432530, 2022). "We analyzed the relationship between the clinicopathologic factors of the HCC patients and their SMYD2 expression and found that SMYD2 is positively correlated with tumor number, tumor size, and age." (PMID 36611819, 2022). "SMYD2-knockout-I CWR-R1ca cells (CWR-R1ca-KO) significantly suppressed the colony formation ability compared to the wild-type cells, allowing us to better understand the role of SMYD2 in tumor cell colony formation." (PMID 35884603, 2022). "Recent studies have shown that overexpression of Smyd2 promotes aerobic glycolysis and reveals a novel link between Smyd2 and tumor metabolism." (PMID 36270984, 2022). "SMYD2 expression levels in tumor and paracancer tissues of 20 NSCLC patients were detected and compared." (PMID 35432530, 2022). "Western blotting analysis of collected primary tumor lysates confirmed the reduction of the SMYD2 expression level in OC-PF-treated primary tumors compared to in the placebo control-treated group." (PMID 35884603, 2022).
tumor (continued). "As SMYD2 promotes tumor growth and metastasis in LUAD and activates RPS7 expression in LUAD cells, we further explored the role of RPS7 in SMYD2-regulated cell carcinogenesis and metastasis." (PMID 33935284, 2021). "Consistent with the results from the public database, SMYD2 mRNA levels in six out of eight samples were significantly higher in LUAD tumor tissues than in the paired adjacent normal tissues." (PMID 33935284, 2021). "We screened 6 potentially downregulated tumor-activating miRNAs (miR-18a-3p, miR-2277-5p, miR-1293, miR-93-3p, miR-5706, and miR-125b) by overlapping the 18 downregulated miRNAs in the SMYD2-knockdown cells with the 97 upregulated miRNAs in the ccRCC samples." (PMID 31754403, 2019). "Similar to CDDP single treatment, single treatment with AZ505, an in vivo available SMYD2 inhibitor, only displayed a slightly inhibition on tumor growth." (PMID 31106145, 2019). "In summary, our findings demonstrate that SMYD2 was overexpressed and acted as a tumor promotor in ccRCC." (PMID 31754403, 2019). "Inhibition of SMYD2 suppressed the progression of ccRCC in vivo and in vitro by dysregulating miR-125b, which acted as a tumor promoting factor in ccRCC." (PMID 31754403, 2019). "The P-gP expression levels in six ccRCC specimens each with the highest and lowest SMYD2 expression levels were measured by IHC; the results indicated that P-gP was upregulated in the tumor tissues with high SMYD2 expression." (PMID 31754403, 2019). "Expression of the SMYD2 protein in paraffin-embedded ccRCC tissues was determined by IHC, and the clinicopathological significance of SMYD2 in the primary tumor samples was determined based on the IHC-staining pattern of the protein." (PMID 31754403, 2019). "The SMYD2 expression levels in the 71 tumor samples were compared to their matched peritumor samples; the results showed that SMYD2 was significantly upregulated in ccRCC (P < 0.0001)." (PMID 31754403, 2019). "The protein lysine methyltransferase SMYD2 has recently emerged as a new enzyme modulate gene transcription or signaling pathways, and involved into tumor progression." (PMID 31106145, 2019). "The results showed that the SMYD2 protein was overexpressed in the ccRCC tumor tissues, compared to the case in the paired, adjacent normal tissues." (PMID 31754403, 2019). "Mechanistically, SMYD2 prompt cell migration, increase the tumor sphere, and block apoptosis, which is dependent on the methylation of p53K370." (PMID 31106145, 2019). "Then we also found that the significant decrease expression of PCNA protein in the SMYD2 knockdown tumor tissues of mice." (PMID 31548876, 2019). "In contrast, tumor growth was inhibited in two SMYD2 knockdown MDA-MB468 cells and MDA MB231 cells as seen by a decrease in tumor sizes compared to the control mice." (PMID 29487338, 2018). "We also found that depletion of SMYD2 decreased tumor cell proliferation assayed by Ki67 staining and induced apoptosis by TUNEL assay." (PMID 29487338, 2018). "In a mouse model of PDAC, in particular, genetic ablation of Smyd2 significantly delayed tumor progression." (PMID 27655694, 2016). "The antiproliferative effects of SMYD2 inhibition in the three tumor types were explored using LLY-507." (PMID 25825497, 2015). "SMYD2 protein was also detected in nine of 12 (75%) HCC patient-derived tumors and all HCC cell lines, although in some of the primary tumor samples, SMYD2 appeared at a slightly higher molecular weight, the explanation of which is not known." (PMID 25825497, 2015). "These collective findings suggest that SMYD2 may modulate signaling networks governing tumor cell proliferation and metastatic processes." (PMID 40777131, 2025). "SMYD2 expression is upregulated in CC cells, suggesting its involvement in tumor metabolism." (PMID 39131609, 2024).
tumor (continued). "Detailed analyses of lung histology demonstrated a nearly 8-fold reduction in the overall number, individual size and overall area of metastatic foci in PyMT;Smyd2 vs PyMT control, and we observed elevated SMYD2 expression in PyMT tumor biopsies obtained from lung metastasis vs primary site." (PMID 38296970, 2024). "However, mammary-epithelium specific SMYD2 ablation increases mouse overall survival by blocking the primary tumor cell ability to metastasize." (PMID 38296970, 2024). "Western blot analysis of collected primary tumor lysates confirmed the reduction of the expression level of the histone methyltransferase SMYD2 (SET and MYND domain-containing protein 2) in oleocanthal-treated primary tumors, as compared to that observed in the placebo control-treated group." (PMID 38139152, 2023). "Hence, it can be concluded that the SMYD2 inhibitor has an anti-inflammatory effect on the mouse lung and suppresses tumor growth by inhibiting the SMYD2 protein." (PMID 37513898, 2023). "Furthermore, the overexpression of SMYD2 was observed in TCGA tumor tissues when GTEx data was used as a control." (PMID 37971632, 2023). "SMYD2 has been identified in normal tissues as well as in tumor cells." (PMID 36838987, 2023). "Targeting tumor SMYD2 is of high oncological therapeutic value." (PMID 35884603, 2022). "We then studied whether SMYD2 regulates CRC cell proliferation in vivo via detecting Ki67-positive cells in tumor tissues from the orthotopic and xenotopic transplant models." (PMID 35022391, 2022). "SMYD2 is widely distributed in normal, pathological, and tumor tissues." (PMID 35432530, 2022). "SMYD2 has the tendency of heterologous distribution of tumor." (PMID 35432530, 2022). "Interference with SMYD2 expression enhances chemotherapy sensitivity of tumor cells." (PMID 35432530, 2022). "After four weeks, we discovered that GLS1 overexpression could promote tumor growth in the SMYD2-knockdown model." (PMID 36611819, 2022). "Therefore, SMYD2 stimulated tumor growth and depressed cell senescence and apoptosis by regulating the EZH2/TET1 axis." (PMID 35668081, 2022). "Baicalein inhibited in SMYD2/RPS7 signaling pathway in tumor cells was also detected by qRT-PCR." (PMID 35432530, 2022). "Interestingly, SMYD2 staining was strongly increased in tumor tissues compared to tumor-free adjacent tissues." (PMID 35022391, 2022). "Next, we sought to determine the potential effect of SMYD2 in tumor metastasis." (PMID 33935284, 2021). "In addition, in vivo studies using mouse models revealed that SMYD2 knockdown or AZ505-mediated SMYD2 inhibition remarkably reduced tumor growth and metastasis." (PMID 33935284, 2021). "IHC analysis revealed that SMYD2 was abundant in both the cytoplasm and nucleus of the tumor cells." (PMID 33935284, 2021). "SMYD2 knockdown resulted in markedly lower tumor volume and weight compared to the control." (PMID 33935284, 2021). "In addition, our data indicated that the inhibition or knockdown SMYD2 inhibit tumor sphere formation and reduce cell migration in NSCLC/CDDP cells, but not in NSCLC parental cells." (PMID 31106145, 2019). "Furthermore, overexpression of SMYD2 protein positively correlates with larger tumor size, more aggressive lymphatic invasion, deeper tumor invasion, and higher TNM stage, as well as worse overall survival rate." (PMID 31370883, 2019). "However, it is still unclear which target genes are regulated by SMYD2 to affect the proliferation of tumor cells, and further studies are therefore needed." (PMID 31548876, 2019). "We then detected the SMYD2 expression in tumor tissues of mice to confirm the silencing efficiency, and the results of immunohistochemistry assay confirmed a significant decrease expression of SMYD2 in SMYD2 knockdown tumor tissues of mice." (PMID 31548876, 2019).
tumor (continued). "SMYD2 was widely distributed in the nucleus and cytoplasm of the ccRCC tumor cells." (PMID 31754403, 2019). "Furthermore, tumor sphere number of NCI-H460/CDDP cells was also obviously reduced by SMYD2 inhibitor and SMYD2 siRNA." (PMID 31106145, 2019). "Thus, our results not only integrate inflammation with epigenetic regulation in TNBC, but also suggest crosstalk between STAT3 and NF-κB in SMYD2 mediated tumor progression." (PMID 29487338, 2018). "It now remains to be seen whether chemical inhibition of SMYD2 or SMYD3 in vivo would affect an already existing tumor and hence be a valuable drug target." (PMID 29856759, 2018). "In-depth investigation of the various substrates of SMYD2 in tumor cell proliferation may now be facilitated using the molecular probe LLY-507." (PMID 25825497, 2015). "To test the role of SMYD2 catalytic function in tumor cell proliferation using LLY-507, we sought to identify tumor types in which SMYD2 could function as a potential driver by means of amplification and/or overexpression." (PMID 25825497, 2015). "Thus, several lines of evidence support a role for Smyd2 in the regulation of proliferation and in tumor progression." (PMID 20305823, 2010). "Expression of PRSS11, MTSS1, CLPTM1 and SMYD2 was determined in tumor samples." (PMID 18601734, 2008). "The upregulation of RPS7 may be crucial for SMYD2-mediated tumor growth and metastasis." (PMID 33935284, 2021). "Recent studies showed that Smyd2 over-expression may be critical in different tumor types, including HPV-unrelated head-and-neck carcinoma, pancreatic ductal adenocarcinoma (PDAC), as well as CLL, where together with SMYD3 it may be associated with the acquisition of complex karyotypic alterations." (PMID 27655694, 2016). "Based on the proliferation data in this study, it is plausible that the mechanisms by which SMYD2 drives tumor cell proliferation may involve more than one substrate and/or a second genetic or epigenetic alteration, and the mechanism(s) of SMYD2 oncogenesis may differ depending on cell type." (PMID 25825497, 2015). "With the exception of ASMTL, we observed upregulated mRNA levels of KIFC2, SMYD2, TFRC, and OPN3 in tumor tissues within these datasets." (PMID 39131609, 2024). "We show that GLS1 is the downstream effector of SMYD2 and is required for SMYD2-regulated HCC tumor growth." (PMID 36611819, 2022). "The results demonstrate correlations among SMYD2, EZH2s, and TET1 expression in the tumor tissues of GIST patients, further verifying the results of the previous experiments from a clinical perspective." (PMID 35668081, 2022). "Later, overexpression plasmids of SMYD2 and EP300 successfully abrogated the anti-tumor effects of sh-LINC01605 in vitro, which corroborated our theory again." (PMID 34544413, 2021). "SMYD2 methylates PTEN at Lysine 313 in vitro and in vivo to negatively regulate PTEN tumor suppressor activity, resulting in activation of the phosphatidylinositol 3-kinase (PI3K)-AKT pathway." (PMID 31370883, 2019). "The mRNA expression study documented a significant increase in the levels of 4 HMTs viz MLL1, MLL2, SMYD2 and NSD2 in tumor tissues." (PMID 31160694, 2019). "High SMYD2 expression was correlated with a higher TNM stage (P = 0.007) and higher incidence of tumor metastasis (P = 0.009)." (PMID 31754403, 2019). "High SMYD2 expression correlated with a high TNM stage (P = 0.007) and early tumor relapse (P = 0.032)." (PMID 31754403, 2019). "SMYD2, EZH2, and SUV420H2 were up‐regulated and SETD7, PRDM1, PRDM8, PRDM6, and PRDM5 were down‐regulated in tumor." (PMID 30984543, 2019). "We also found that knockdown of SMYD2 and inhibition of SMYD2 with its specific inhibitor, AZ505, prevented tumor growth in TNBC cells implanted nude mice." (PMID 29487338, 2018). "Our study has shown for the first time the effect of the specific SMYD2 inhibitor, AZ505, in an in vivo disease model and it clearly delayed tumor growth in TNBC xenografts implanted nude mice." (PMID 29487338, 2018).